HPSE2 (heparanase 2 (inactive))
Description:
Binds heparin and heparan sulfate with high affinity, but lacks heparanase activity. Inhibits HPSE, possibly by competing for its substrates (in vitro).
Synonyms: Hpa2; HPR2; UFS; UFS1
Tractability: Antibody: UniProt places it where antibodies can reach, with high confidence; its Gene Ontology location is reachable by antibodies, with high confidence; UniProt predicts a signal peptide or a membrane-spanning region.
Gene: Protein-coding gene on chromosome 10 (98,457,077 to 99,235,862, reverse strand). Ensembl gene ENSG00000172987.
Subcellular location: Secreted, extracellular space, extracellular matrix
Pathways (Reactome):
Metabolism: HS-GAG degradation
Gene Ontology:
Molecular function: heparan sulfate proteoglycan binding; heparanase activity; protein sequestering activity; hydrolase activity, acting on glycosyl bonds
Biological process: extracellular matrix organization; heparan sulfate proteoglycan catabolic process
Cellular component: extracellular matrix; plasma membrane; membrane
Genetic constraint (gnomAD): Loss-of-function variants: 32 observed, 51.35 expected, observed/expected ratio (o/e) 0.62, 90% interval 0.47 to 0.84. The upper end of that interval is the gene's LOEUF score, 0.84, which puts it in group 3 of 6, group 1 being the genes least tolerant of losing a copy. Missense variants: 679 observed, 724.47 expected, observed/expected ratio (o/e) 0.94, 90% interval 0.88 to 1. Synonymous variants: 287 observed, 291.42 expected, observed/expected ratio (o/e) 0.98, 90% interval 0.89 to 1.09.
Homologues: Orthologues: chimpanzee HPSE2 (100% identical), macaque HPSE2 (99% identical), pig HPSE2 (99% identical), dog HPSE2 (99% identical), rabbit HPSE2 (99% identical), mouse Hpse2 (97% identical), rat Hpse2 (96% identical), guinea pig HPSE2 (90% identical), tropical clawed frog hpse2 (80% identical), zebrafish hpse2 (67% identical), Drosophila melanogaster CG14309 (22% identical). Paralogues in human: HPSE (40% identical).
Diseases named in the same sentence as HPSE2 in open-access papers:
HPSE2 is named in the same sentence as 46 diseases in open-access papers, as found by Europe PMC text mining. Sharing a sentence is not in itself a finding about the gene and the disease. The quoted sentences say what the papers report.
urofacial syndrome (14 papers, 2014 to 2025). "This is best demonstrated by the finding that HPSE2 is mutated in urofacial syndrome (UFS), a rare autosomal recessive inherited disease." (PMID 38519456, 2024). "Mutations in HPSE2 have been associated with urofacial syndrome in humans, suggesting a potential developmental role." (PMID 33643179, 2020). "For the human all-tissues network, the genes MC2R and HPSE2 are central and related to diseases: glucocorticoid deficiency and urofacial syndrome respectively." (PMID 29161290, 2017). "Interestingly, HPSE2 mutations in humans are associated with urofacial syndrome (UFS), also known as Ochoa disease." (PMID 40899692, 2025). "Heparanase 2 (HPSE2) encodes a specific enzyme and is associated with urofacial syndrome." (PMID 24337368, 2014). "Similarly, identification of HPA2 protein in neurons has also been previously reported in a study investigating the role of HPSE2 in urofacial syndrome (OMIM#236730), a rare condition associated with dysuria and typified by unusual facial expressions." (PMID 25339718, 2014). "Mutations of HPSE2 were identified in patients diagnosed with urofacial syndrome (UFS), a rare genetic disorder that exhibits abnormal facial expression and bladder voiding dysfunction, leading to renal damage and eventually renal failure." (PMID 37491420, 2023). "Urofacial syndrome (UFS) is a rare autosomal recessive disorder characterized by voiding dysfunction, inverted facial expressions when smiling, and potential mutations in LRIG2 or HPSE2 genes." (PMID 40948727, 2025). "The only known role for Hpse2 (an in-active splice variant of Hpse) specifically in the PNS is in the development of urofacial syndrome, where Hpse2 knock-out perturbs the correct development of motor neurones via fibroblast growth factor (FGF) mediated gene transcription." (PMID 29581478, 2018). "Several monogenic causes of other congenital bladder outflow obstruction disorders have been described including BNC2 in urethral stenosis; FLNA in syndromic urethral anomalies; HPSE2 and LRIG2 in urofacial syndrome; CHRM3 in prune-belly like syndrome; and MYOCD in megabladder." (PMID 36124557, 2022).
breast carcinoma (5 papers, 2019 to 2025). "Altogether, our results revealed that miR-15b-5p accelerates breast cancer progression via disinhibiting HPSE2, simultaneously providing a novel diagnostic and prognostic marker and a potential therapeutic target." (PMID 32175269, 2020). "HPSE1 and HPSE2 have been detected by immunocytochemistry in peripheral blood mononuclear cells isolated from a breast cancer patient, and their levels are higher than in a healthy woman." (PMID 40899692, 2025). "In contrast to HPSE1, which is mainly overexpressed in pathological processes, HPSE2 is weakly expressed in many cancers, such as gastric and breast cancers and in turn behaves as a tumor suppressor." (PMID 40899692, 2025). "In breast cancer-promoting breast cancer cell proliferation, migration, and invasion, hsa-miR-15b-5p availability significantly decreased HPSE2 expression at both the mRNA and protein levels." (PMID 36066672, 2022). "Based on the microarray analysis and bioinformatics analysis, we focused on HPSE2, which has been found to act as a suppressor gene in a variety of tumors including breast cancer." (PMID 32175269, 2020). "In summary, we showed that miR-15b-5p promotes breast cancer cell proliferation, migration, and invasion by directly targeting HPSE2." (PMID 32175269, 2020). "Knockdown of miR-15b-5p significantly increased HPSE2 expression at both mRNA and protein levels in breast cancer cells in vitro." (PMID 32175269, 2020). "The apoptosis rate of breast cancer cells by the miR-15b-5p inhibitor was also reversed after co-transfection with HPSE2 siRNA." (PMID 32175269, 2020). "Meanwhile, IHC showed that HPSE2 expression in breast cancer tissues (25%) was prominently lower compared with that in the adjacent normal tissues (58%, P < 0.0001)." (PMID 32175269, 2020). "We propose to conduct this study on both isoforms of heparanase, namely heparanase-1 (HPSE) and heparanase-2 (HPSE2), in the context of breast cancer." (PMID 33053017, 2020). "According to TCGA databases, the expression of miR-15b-5p is negatively related to HPSE2 in breast cancer patients (R = −0.1580, P = 1.81e−07)." (PMID 32175269, 2020). "We used ISH and IHC to evaluate the differential expression of miR-15b-5p and HPSE2 mRNA and protein in breast cancer tissues and adjacent tissues." (PMID 32175269, 2020). "The overexpression of HPSE2 in circulating lymphocytes of breast cancer patients has previously been described by our group." (PMID 30922347, 2019). "The immunocytochemistry analysis clearly demonstrated the increased expression of both isoforms of heparanase (HPSE and HPSE2) in T-lymphocytes exposed to the plasma of breast cancer patients or to MCF-7 cells." (PMID 30922347, 2019). "There was a significant increase in the mRNA level of both heparanases (HPSE and HPSE2) when T-lymphocytes were exposed to plasma of breast cancer patients or to co-culture medium, confirming the previous results obtained by immunocytochemistry." (PMID 30922347, 2019). "Elevated expression of HPSE2 is positively correlated with a better prognosis for breast cancer." (PMID 32175269, 2020). "According to the data from TCGA database, HPSE2 is underexpressed in breast cancer tissues." (PMID 32175269, 2020). "The expression level of miR-15b-5p in breast cancer is negatively correlated with HPSE2." (PMID 32175269, 2020). "To determine whether HPSE2 could reverse the oncogenic effects of miR-15b-5p, we co-transfected breast cancer cells with miR-15b-5p inhibitor and HPSE2 siRNA according to the experimental design from previous reported." (PMID 32175269, 2020). "Moreover, Theodoro and colleagues observed increased levels of HPSE and HPSE2 in peripheral blood mononuclear cells (PBMCs) of breast cancer patients." (PMID 30922347, 2019). "Thus, our results confirm that miR-15b-5p may mediate its carcinogenic effects in breast cancer by inhibiting HPSE2 expression." (PMID 32175269, 2020).
breast carcinoma (continued). "Furthermore, correlation of HPSE and HPSE2 in different human breast cancers was addressed to answer if both heparanases could be a useful marker to differentiate among such subtypes of cancer." (PMID 33053017, 2020). "Lymphocytes collected from healthy women were incubated in the presence of MCF-7 breast cancer cells (co-culture) to stimulate HPSE and HPSE2 overexpression." (PMID 30922347, 2019). "We next revealed a negative correlation between miR-15b-5p and heparanase-2 (HPSE2) expression in breast cancer." (PMID 32175269, 2020). "PBMCs were allowed to adhere in cell culture in the presence of phorbol ester (PMA), and after 24 h, non-adherent cells were incubated with the plasma of breast cancer patients; the expression of HPSE and HPSE2 was significantly enhanced in these cells." (PMID 30922347, 2019).
malaria (4 papers, 2014 to 2025). Malaria is a serious and sometimes fatal disease caused by a parasite that commonly infects a certain type of mosquito which feeds on humans. "Similarly, CSMD1 and the HBE1, HBG2 and HPSE2 genes were identified as candidates for positive selection in both NA and WEA populations, probably because of the historical presence of malaria in both Sub-Saharan Africa and the Mediterranean region as a common selective pressure." (PMID 37210386, 2023).
breast tumor (3 papers, 2013 to 2024). "Therefore, the oncogenicity of miR-15b-5p on the tumorigenesis of breast tumor cell lines shown in this work could be credited in part to its modulation of HPSE2." (PMID 32175269, 2020). "C2 and C5 mainly resided in breast tumors and expressed tumor suppressor genes (EXT1 and HPSE2), which may regulate the heparan sulfate in the breast TME; C13 mainly resided in breast NAT and highly expressed LRP1B, a putative tumor suppressor that may inhibit cancer migration and invasion." (PMID 38010945, 2024). "In contrast, HPSE2, a homologue of HPSE that is able to interact with HS with high affinity, hence it being proposed to have anti-cancer properties, exhibited strong underexpression in all the patients studied, pointing to this gene having an important role in breast tumor progression." (PMID 23327652, 2013).
colorectal cancer (3 papers, 2015 to 2025). A primary or metastatic malignant neoplasm that affects the colon or rectum. "Likewise, HPSE2 was suggested as a good tumor marker, better than HPSE, for the first time only in 2008 in colorectal carcinoma in comparison with normal mucosa with sensitivity of 98% and specificity of 100% using immunohistochemistry technique." (PMID 26488476, 2015). "For instance, 5′tiRNA-Pro-TGG may facilitate the progression of serrated pathway colorectal cancer (CRC) by modulating metabolic and immune pathways through its interaction with HPSE2 and regulation of HPSE2 expression in sessile serrated lesions (SSLs) and BRAF-mutant CRC." (PMID 41357206, 2025).
migraine (3 papers, 2020 to 2024). "In summary, interaction analysis indicated that intergenic rs12128399, rs6660757 and variants in HPSE2, REST and from the 1p31.1 region (including ADGRL2) represent lifetime depression-dependent genetic factors for migraine." (PMID 34972135, 2021). "In summary, analyses presented in this paper validate polymorphisms in p31.1 region of chromosome 1, PRDM16, ADGRL2, REST and HPSE2 genes in migraine." (PMID 34972135, 2021). "Furthermore, this study also provides evidence that SNPs of the previously identified migraine risk genes REST, ADGRL2, HPSE2 and 1p31.1 show lifetime depression-dependent associations with the disease." (PMID 34972135, 2021). "Furthermore, results allowed the separation of variants that play a role in migraine accompanied by depression, like ADGRL2, REST and HPSE2, from those that play a general role in migraine, like PRDM16." (PMID 34972135, 2021). "While the p31.1 region and PRDM16 are worthy of further investigations in migraine in general, REST, HPSE2 and ADGRL2 may be prime candidates behind migraine pathophysiology in patients with comorbid depression." (PMID 34972135, 2021). "In contrast, intergenic rs6660757 and rs12128399, rs1889974 in HPSE2, rs11163394 in ADGRL2 and rs1043215 of REST may only serve as biomarkers in migraine accompanied by lifetime depression." (PMID 34972135, 2021). "For example, selectivity of the rs12260159 (HPSE2) was significantly preferential for migraine without aura (“inverse subset”) among the fully qualifying migraineurs (pcor = 0.002) but not selected for association by the BIC in the larger samples including non-qualifying, self-reported migraineurs." (PMID 33643179, 2020).
renal failure (3 papers, 2014 to 2023). "In this study, we aimed to investigate whether inhibition of HPSE1 activity by HPSE2 is a promising therapeutic strategy to target albuminuria and renal failure associated with glomerular diseases." (PMID 37180718, 2023). "We postulate that inhibition of HPSE1 activity by HPSE2 is a promising therapeutic strategy to target albuminuria and resulting renal failure." (PMID 37180718, 2023).
depression (2 papers, 2021 to 2024). "In addition, HPSE2 associated with the depression-related trait, neuroticism." (PMID 34972135, 2021). "Bayesian relevance analysis confirmed the relevance of intergenic rs6660757 and rs12128399 (p31.1), rs1043215 (REST), rs1889974 (HPSE2) and rs11163394 (ADGRL2) from depression interaction results, and the moderate relevance of rs77864828 and rs2455107 of PRDM16 from main effect analysis." (PMID 34972135, 2021).
psoriasis (2 papers, 2021 to 2025). An autoimmune condition characterized by red, well-delineated plaques with silvery scales that are usually on the extensor surfaces and scalp. "We can also observe an increased mRNA expression of HPSE2 in the Psoriasis Group than the Control Group (0.0940 ± 0.1342 versus 0.0023 ± 0.0021) p = 0.0005." (PMID 34715781, 2021). "Our study was a pioneer in showing higher levels of HPSE2 expression in the patient’s skin area affected by psoriasis plaque." (PMID 34715781, 2021). "Taken together, the significant changes in the expression of HPSE, HPSE2, SYND1 in the skin affected by psoriasis confirm alterations of ECM in such disease." (PMID 34715781, 2021). "The mRNA expression of HPSE2 was also significantly higher in the Psoriasis group compared to the Non-affected tissue of patients with psoriasis 0.0940 ± 0.1342 versus 0.0109 ± 0.0134 (p = 0.0349)." (PMID 34715781, 2021). "There was also increased expression of HPSE2 even in a non-psoriatic area from patients with psoriasis, showing that HPSE2 might be highly expressed in the initial stages of the disease." (PMID 34715781, 2021). "The significant increase in the expression of heparanase-1 (HPSE), heparanase-2 (HPSE2), syndecan-1 (SYND1), metalloproteinase-9 (MMP9), and tissue inhibitor of metalloproteinase 2 (TIMP2) in biopsies of skin affected by psoriasis showed extracellular matrix alterations in psoriasis." (PMID 34715781, 2021). "Although there are no reports in the literature that correlates psoriasis with HPSE2, it is known that HPSE2 shows no catalytic activity over heparan sulfate but presents a high affinity for heparin and heparan sulfate, which can modulate the activity of the enzyme HPSE." (PMID 34715781, 2021). "A significant increase in protein and mRNA expression was observed in both heparanases (HPSE and HPSE2), and higher protein levels of MMP9 and TIMP2 were observed in the psoriasis plaque compared to the non-affected skin." (PMID 34715781, 2021). "HPSE2, SYND1, MMP9, and TIMP2 have higher protein expression in the non-affected skin tissue of patients with psoriasis than control tissues, indicating that increased expression of such molecules possibly occurs in the initial stages of the disease even in the absence of psoriatic plaque." (PMID 34715781, 2021). "Moreover, there was a significant increase in HPSE2, SYND1, MMP9, and TIMP2 in non-affected skin samples from patients with psoriasis than in the control sample (tissue obtained by individuals who do not have psoriasis)." (PMID 34715781, 2021).
Sepsis (2 papers, 2019 to 2023). Sepsis is defined as life-threatening organ dysfunction caused by a dysregulated host response to infection. "Thus, loss of HPSE2 can promote microcirculatory disorder in sepsis leading to organ failure." (PMID 31537875, 2019). "In polymicrobial CLP mouse sepsis model the expression of HPSE2 in renal medullary capillaries was decreased." (PMID 31537875, 2019). "In vivo, expression of HPSE2 in plasma and kidney medullary capillaries was decreased in mouse sepsis model." (PMID 31537875, 2019). "Our data showed decreased plasma HPSE2 expression in mouse sepsis models indicating that cross-talk of the heparanases is important in vivo." (PMID 31537875, 2019). "To investigate how expression of endogenous HPSE2 is regulated during sepsis, we used the mouse CLP polymicrobial sepsis model." (PMID 31537875, 2019). "This expression of HPSE2 was strongly downregulated in sepsis." (PMID 31537875, 2019).
asthma (1 paper, 2022). "Differential methylation of HPSE2 has been shown to be associated with FEV1 in older age and genetic variants in HPSE2 have been associated with childhood onset asthma." (PMID 35906571, 2022).
bladder disease (1 paper, 2019). "Our observations provide strong evidence that a peripheral neuropathy is part of the pathobiology of UFS bladder disease, whether caused by HPSE2 or LRIG2 variants." (PMID 30885509, 2019).
differentiated thyroid carcinoma (1 paper, 2015). Differentiated thyroid carcinoma (DTC), also known as papillary or follicular thyroid carcinoma, is a slow-growing malignancy usually presenting in adults as an asymptomatic thyroid mass. "It was also noted that enhanced HPSE2 expression and high levels of HPSE enzymatic activity may be strongly indicative of DTC, suggesting that both heparanases may be directly involved in the carcinogenesis of differentiated thyroid carcinoma." (PMID 26488476, 2015).
dyslipidemia (1 paper, 2024).
follicular carcinomas (1 paper, 2015). "HPSE2 expression was detected in the neoplastic cells of all 61 specimens of DTC (including classic and follicular variant of PTC and also in all cases of follicular carcinomas) and in 79 cases (46.7%) of benign lesions." (PMID 26488476, 2015).
gastric cancer (1 paper, 2015). A primary or metastatic malignant neoplasm involving the stomach. "Moreover, HPSE2 was also associated with the diagnosis of ovarian cancer with accuracy of 78% and recently with better outcomes in patients with gastric cancer." (PMID 26488476, 2015).